VIM (vimentin)
Diseases named in the same sentence as VIM in open-access papers (continued):
Sharing a sentence is not in itself a finding about the gene and the disease.
lung carcinoma (continued). "The results of the analysis of the influence of overexpression of circANXA2 on the expression levels of epithelial marker E-cadherin and mesenchymal marker vimentin in lung cancer cells showed that overexpression of circANXA2 inhibited the expression of E-cadherin but upregulated vimentin." (PMID 34992655, 2021). "Additionally, it was shown that exosomes acquired from late-stage lung cancer patient serum had increased vimentin expression, and a more metastatic phenotype was induced in recipient cells." (PMID 33855679, 2021). "Vimentin may be the critical regulator of lung cancer cell movement, metastasis, and EMT through OPN‐PI3K and/or OPN‐MEK pathways." (PMID 34323425, 2021). "Interestingly, decreased E-cadherin expression and increased Vimentin expression were also observed in lung cancer tissues." (PMID 33748140, 2021). "Immunoblot analyses of lung tissue or metastatic lung cancer tissue from each mouse revealed that mesenchymal markers, including N-cadherin, vimentin, α-SMA, snail, and slug, were increased in lung tissue expressing TD compared with those expressing mock, WT, or FA." (PMID 31548612, 2020). "To determine whether epithelial-mesenchymal transition (EMT) is involved in TCO-mediated antitumor effect in lung cancer cells, we examined the expressions of E-cadherin, N-cadherin, Vimentin, and Snail1 in TCO-treated cells." (PMID 33614493, 2020). "Moreover, vimentin knock-down in the lung cancer cell line A549 led to slower and less directed migration." (PMID 31940801, 2020). "However, a different study showed that lung cancer cells that had vimentin IFs extended into lamellipodia showed more effective migration compared to cells that had vimentin-free lamellipodia." (PMID 31940801, 2020). "Interestingly, citrullinated vimentin has been found elevated in serum from lung cancer patients supporting a rationale for targeting vimentin as a liquid biopsy biomarker in this disease." (PMID 31827725, 2019). "Indeed, the impact of miR-33a over-expression on β-catenin, vimentin, and snail protein levels is less pronounced in lung cancer cells over-expressing RASSF1C as one would predict." (PMID 30719208, 2019). "Finally, in the oncology setting, extracellular vimentin has been evaluated in patients with Sezary syndrome, malignant melanoma and lung cancer." (PMID 31827725, 2019). "In contrast, RASSF1C over-expression has been demonstrated by us and others to up-regulate β-catenin gene expression in lung cancer cells; and in this study, we also show that lung cancer cells over-expressing RASSF1C exhibit increased vimentin and snail protein levels." (PMID 30719208, 2019). "Thus, we wanted to determine if RASSF1C over-expression will attenuate the effects of miR-33a on β-catenin as well as vimentin and snail in lung cancer cells." (PMID 30719208, 2019). "Furthermore, IL-6 inhibition dramatically suppressed MMP2/9 and vimentin expression but elevated E-cadherin expression all four lung cancer cell lines treated with aADSCs-CM." (PMID 31196220, 2019). "In conclusion, the abnormal Ang-2 expression promoted cell proliferation and affected on abilities of invasion, metastasis, and EMT of lung cancers that should provide a new mechanism insight into tumor metastasis by inhibiting E-cadherin and upregulating VIM, Twist and Snail signaling." (PMID 29560103, 2018). "As our results indicated that rVAR2-captured CTCs could contain a mesenchymal subpopulation, we stained CTC enriched samples from two lung cancer patients for the mesenchymal marker vimentin." (PMID 30115931, 2018). "In summary, the present results demonstrated that the combination of fisetin with paclitaxel inhibited the migration and invasion of A549 human lung cancer cells by modulating the expression of metastasis-related genes and disrupting the structure of actin and vimentin cytoskeleton." (PMID 29495431, 2018).
lung carcinoma (continued). "Finally, in HT29 colorectal adenocarcinoma and A549 lung carcinoma cell line models, norepinephrine-induced Snail and vimentin expression were inhibited by Galunisertib." (PMID 29774119, 2018). "Furthermore, vimentin overexpression in non–small-cell lung cancer is an independent prognostic factor for poor survival." (PMID 30248895, 2018). "The expression of E-cadherin, a hallmark of the epithelial phenotype, was decreased, whereas the expression of vimentin, a typical marker of the mesenchymal phenotype, was increased when lung cancer cells were co-cultured with CAFs in which SNAI1 was upregulated." (PMID 29383119, 2017). "We demonstrated successful knockdown of vimentin in exosomes derived from lung cancer serum." (PMID 27363026, 2016). "Therefore, this tumor model recapitulates human lung cancer as it yields distant metastatic foci, which correlates with the down-regulation of E-cadherin and the up-regulation of Vimentin." (PMID 28105457, 2016). "Importantly, curcumin reversed HGF-induced EMT markers changes, causing reinduction of E-cadherin and reinhibition of vimentin expression in a concentration dependent manner, indicating that curcumin has inhibitory effects on HGF-induced lung cancer cell EMT." (PMID 27525306, 2016). "Our findings suggest that exosomes might be a potential driver of metastatic lung progression and vimentin could be an activator of exosome-induced metastasis in human lung cancer." (PMID 27363026, 2016). "Immunofluorescence staining confirmed that ALDHbr cells co-expressed vimentin in fresh xenografted lung cancer tissues, indicating the fresh lung cancer cells express multiple potential cancer stem cell markers and some of these cells also possess EMT properties." (PMID 25796627, 2015). "For live-cell imaging we introduced vimentin-specific chromobodies into a lung cancer cell model." (PMID 26292717, 2015). "Vimentin was negatively expressed in normal bronchial epithelial tissues, while the rate of positive expression was increased to 32% (25/78) in the lung cancer tissue." (PMID 24505377, 2014). "In addition, vimentin is over-expressed in many epithelial cancers, including lung cancer, and its over expression in cancer correlates with tumor growth, invasion, and poor prognosis." (PMID 24274066, 2013). "Our results revealed that IL-27-treated lung cancer cells show increased epithelial marker (E-cadherin and γ-catenin), decreased Snail (transcriptional repressor of E-cadherin), and decreased mesenchymal marker (N-cadherin and vimentin) expression." (PMID 24274066, 2013). "VIM is not believed to be associated with survival in lung cancer, although S100A4 has been correlated with prognosis of lung squamous cell carcinoma in clinical research studies." (PMID 22761930, 2012). "We found that EMT markers N-cadherin and Vimentin were downregulated in lung cancer H1299 cells stably overexpressing Kindlin-1 compared with the control cells expressing Flag-BAP, suggesting a role of Kindlin-1 in inhibition of EMT program in lung adenocarcinoma cells." (PMID 23209705, 2012). "Furthermore, cytokeratins and vimentin are used in the diagnosis of lung cancer and lower intestinal cancer." (PMID 19367286, 2009). "Thus, the low expression of IFFO1 in lung cancer promoted cell migration and movement, which might be due to an enhancement of N-cadherin, Vimentin, and Cdc42 expression levels." (PMID 40634295, 2025). "However, no causal in vivo studies linking vimentin and non–small cell lung cancer (NSCLC) progression existed until now." (PMID 37161053, 2023). "Notwithstanding the multiple systematic meta-analysis that addressed the impact of Sox2, nestin, and vimentin as independent predictors in human lung cancer prognosis, two reports demonstrated the clinicopathological and prognostic significance of the nucleolin expression in lung cancer patients." (PMID 35565346, 2022).
lung carcinoma (continued). "Similarly, the combination treatment inhibited vimentin and n-cadherin in A549 lung cancer cells." (PMID 35337178, 2022). "Moreover, the mRNA expression of VIM in serum-derived exosomes from late stage lung cancer patients was significantly higher than that in exosomes from healthy individuals and early stage lung cancer patients." (PMID 35158999, 2022). "To examine whether the induction of EMT reduces HER2 expression, we analyzed mRNA expression of ERBB2, epithelial phenotype markers CDH1, EPCAM, MUC1 and OCLN, mesenchymal phenotype markers CDH2, FN1, SNAI2, and VIM in the A549 cell line (HER2-high human lung cancer epithelial cell line)." (PMID 34575017, 2021). "How the vimentin network regulates tumor metastasis and lung cancer survival remains unclear." (PMID 33963314, 2021). "Similarly, human LAD specimens showed colocalization of VAL and Vimentin in the cytoplasm of lung cancer cells, and LAD specimens carrying activating PIK3CA (E545K) mutation presented increased staining intensities of both VAL and Vimentin as compared to those carrying wild-type PIK3CA or AKT." (PMID 33046716, 2020). "MSCs can fuse with various tumor cells, and when spontaneous cell fusion occurs between lung cancer cells and bone marrow MSCs, the tumorigenicity of the resultant fusion cells is significantly enhanced, with expression of interstitial cell markers, vimentin and fibronectin." (PMID 32632040, 2020). "In human lung cancer samples, increased vimentin and slug expression and decreased E-cadherin expression were found in the groups with high FoxM1 expression, while decreased vimentin and Slug expression and increased E-cadherin expression in the groups with low FoxM1 expression." (PMID 23536876, 2013). "NE significantly enhanced lung cancer cell proliferation, specifically upregulated PFKFB3 mRNA expression, promoted EMT marker (N-cadherin and Vimentin) expression, and increased cell migration capacity." (PMID 42157854, 2026). "Previous studies in lung cancer have demonstrated that CHEK1 activates the Snail transcription factor, which suppresses E-cadherin and upregulates N-cadherin and Vimentin, thereby inducing EMT and promoting tumor cell migration and invasion." (PMID 41564103, 2026). "In this study, we demonstrated that LncPTEN1 promotes ubiquitination of Vimentin mediated by Trim16 to facilitate Vimentin degradation, thereby inhibiting the EMT process and suppressing lung cancer metastasis." (PMID 40521243, 2025). "Further, co-culture experiments with lung cancer cells and human embryonic lung WI-38 cells showed increased expression of α-SMA, FN1, and VIM in WI-38 cells, along with significantly enhanced migration capacity." (PMID 40331946, 2025). "The western blot assay was used for the detection of EMT marker proteins, and down-regulation of E-cadherin and up-regulation of N-cadherin and vimentin proteins were observed after ROB renting, suggesting that ROB inhibits the metastasis of lung cancer cells." (PMID 39450260, 2024). "Considering the regulatory effect of XRCC2 on vimentin stability, we aimed to investigate the involvement of XRCC2 in lung cancer metastasis." (PMID 39090304, 2024). "It has been shown that RYBP inhibits the progression and metastasis of lung cancer by suppressing EGFR signaling and EMT, and high levels of PKP1 are important to maintain a high expression of vimentin, which is a key regulator of EMT and metastasis." (PMID 38785968, 2024). "Studies have shown that cell surface vimentin (CSV) is more efficient than EpCAM in capturing CTCs in solid tumors, including lung cancer." (PMID 39085849, 2024). "In this study, we show that ALD-R491, a small molecular compound that specifically increases the stability and suppresses the dynamic exchange of units within vimentin intermediate filaments, partially reverses the EMT phenotypes of human lung cancer cells." (PMID 39796712, 2024).
lung carcinoma (continued). "To clarify the role of the intermediate filament protein vimentin in the epithelial-to-mesenchymal transition (EMT), we induced EMT in lung cancer cells with TGF-β1, followed by treatment with the drug ALD-R491, which targets vimentin." (PMID 39796712, 2024). "Treating lung cancer cells with BSP inhibited the protein and mRNA expression of E‐cadherin and promoted vimentin expression, whereas inhibiting BSP expression had the opposite effects." (PMID 39466654, 2024). "Metastasis cancer studies, including those of lung cancer, have demonstrated that STAT3 is essential for maintaining Slug, Snail, and Vimentin expression." (PMID 39195486, 2024). "Knockdown of PZ decreases cell wound healing capacity, migration, invasion, and the protein levels of Slug, Vimentin, and N-cadherin in A549 cells, indicating that PZ modulates metastasis and invasion through the EMT pathway in lung cancer cells." (PMID 37528887, 2023). "Immunofluorescence analysis revealed suppressed vimentin expression in NSCLC cell lines treated with MP06, which is consistent with the inhibited expression levels in MP06-treated lung cancer cell lines." (PMID 38132928, 2023). "Further analyses found that with decreased FGF14 expression in lung cancer cells, the expression of p-ERK/ERK, N-cadherin, and Vimentin increased, but the expression of E-cadherin decreased." (PMID 38040694, 2023). "Like in mouse lung cancer, many cells with HS2/HS3 transcripts were co-localized with fibroblast markers αSMA or vimentin." (PMID 36635266, 2023). "Upon addition of curcumin to radiation therapy, the expressions of E-cadherin, vimentin and SLUG, which are crucial EMT markers and promoters of invasion, were decreased, ultimately leading to the inhibition of EMT properties in A549 lung cancer cells." (PMID 36015440, 2022). "Hsa_circ_0006692 modulated EMT of lung cancer cells via the stimulation of CDH1, CDH2, VIMENTIN, and MMP7." (PMID 35627232, 2022). "The combination treatment inhibited invasion and migration of lung cancer cells, as shown by the downregulation of MMP9, Vimentin and N-cadherin, while overexpressing the E-cadherin expression level." (PMID 36015440, 2022). "In previous studies, vimentin, which is highly involved in EMT and metastasis, was reported as the primary target of Arylquin 1 to inhibit the spread of lung cancer." (PMID 35628455, 2022). "Here, we found that FOXA1 knockdown decreased CDH1 (epithelial marker) but increased CDH2, VIM, SNAI2, and PTHLH (mesenchymal markers) in A549 lung cancer cells." (PMID 35897813, 2022). "Previous studies have demonstrated that TCF4 can interact with TWIST1 to promote the expression of EMT-related genes, such as CDH2, VIM, SNAI1, and SNAI2, in embryonic stem and lung cancer cells." (PMID 35406121, 2022). "A549 and H1299 lung cancer cells were induced to undergo via TGF-β1 treatment, resulting in the downregulation of E-cadherin and upregulation of N-cadherin and Vimentin concurrently with increases in the migration and invasion capacities of the cells." (PMID 34829545, 2021). "In lung cancer cells, the inhibition of Id1 expression reduces the expression of EMT-related markers (vimentin, intergrin-β, and snail)." (PMID 33936204, 2021). "For example, Rab7 expression regulated the migratory ability of lung cancer H1299 cells through Ras-related C3 botulinum toxin substrate 1 (RAC1) and vimentin." (PMID 33888099, 2021). "There are reports that BAP31 knockdown reduces expression level of TGF-β1, MMP-2, MMP-9, ROCK1, α-SMA, Vimentin and N-cadherin in cervical cancer, and BAP31 affects F-actin distribution to promote migration and invasion of lung cancer cells." (PMID 34179078, 2021). "Expression levels of the lung cancer marker proteins MYC, EGFR, and vimentin are also altered by the aberrant expression of BCL2L1." (PMID 34193120, 2021).
lung carcinoma (continued). "In this study, we found that alectinib and lorlatinib significantly reduced the expression of VIM, FN1, MMP-9, and MMP-7 and that finally inhibited the metastasis of lung cancer cells." (PMID 33091333, 2021). "To further verify the ability of Gimap5 to regulate lung cancer metastasis, we studied the effect of Gimap5 on the expression levels of EMT biomarkers (E-cadherin, N-cadherin, Snail, Slug, Twist, ZO-1, Vimentin) in PC9, A549 and 1299 cells." (PMID 34604035, 2021). "Treatment of lung cancer cells with phoyunnanin E decreases the levels of active AKT/FAK, integrin-mediated migration, and the expression of EMT markers such as N-cadherin, vimentin, snail, and slug." (PMID 34279440, 2021). "As an epithelial marker, CDH1, was decreased and mesenchymal markers, CDH2, VIM, SNAI2, and ITGA5 were increased in PGC1α-silenced epithelial types of A549, H358, and Calu-1 lung cancer cells." (PMID 33917757, 2021). "In lung cancers, RUNX2 overexpression was shown to promote EMT via direct regulation of vimentin along with other proteins." (PMID 32204402, 2020). "Knockdown of PD-L1 suppressed the expression of N-cadherin, Vimentin, MMP-9 and Claudin-1 but upregulated E-cadherin expression in lung cancer cells." (PMID 32632098, 2020). "Saracatinib (AZD0530) targets Fyn and inhibits the growth of lung cancer cells that are resistant to ALK inhibitors, interestingly, this compound also suppresses Fyn induced invasion and metastasis by decreasing Vimentin and Snail." (PMID 32565740, 2020). "The mRNA and protein expression of EMT markers Vimentin, Zeb1, Snail, and Slug were markedly increased in PC9 lung cancer cells co-cultured with MSCs compared to PC9 cells cultured in the absence of MSCs." (PMID 33119681, 2020). "In 60 patients with lung cancer, using 2 CTC per 7.5 mL blood as cutoff value, the positive rates of EGFR, Vimentin and FA magnets used alone and in combination were 65.0%, 33.3%, 93.3% and 100%, respectively." (PMID 32336066, 2020). "They demonstrated that TDE derived from highly metastatic lung cancer cells and serum from late-stage lung cancer patients induced EMT through vimentin overexpression in human bronchial epithelial cells." (PMID 32793478, 2020). "Fresh lung cancer and paracancer tissue specimens were collected from 30 patients, and the expression of BTBD7, E-cadherin, N-cadherin, fibronectin, and vimentin was analyzed by qRT-PCR, western blotting, and immunohistochemistry." (PMID 31886230, 2019). "In this study, the decreased E-cadherin and increased N-cadherin and Vimentin were found in cisplatin-resistant EOC cells compared with parental cells, which is consistent with the findings from other groups in EOC and lung cancer." (PMID 31234823, 2019). "The four lung cancer cell lines treated with aADSC-CM exhibited a significant increase in MMP2/9 and vimentin expression and a decrease in E-cadherin expression." (PMID 31196220, 2019). "In summary, we found that BTBD7 is highly expressed in lung cancer tissues and A549 cells and induces EMT mainly by downregulating E-cadherin and upregulating N-cadherin, vimentin, and FN." (PMID 31886230, 2019). "The increasing evidences suggested that high vimentin expression correlated well with the clinicopathological characteristics in other cancers such as cholangiocarcinoma (CCA), lung cancer, and liver cancer." (PMID 29955607, 2018). "The two systems were tested on the basis of expression levels of the genetic markers vimentin, E-cadherin, N-cadherin and GAPDH in A549 lung carcinoma cells at two known concentrations." (PMID 29467444, 2018). "E-cadherin and vimentin were found to be prognostic factors for both DFS and OS for lung cancer and oral squamous cancer." (PMID 28744307, 2017). "Decreased expression of miR-200 up-regulates its target genes, namely CDH1 (also known as E-cadherin), VIM (also known as vimentin), ZEB1, and ZEB2, which leads to EMT as lung cancer progresses." (PMID 28486418, 2017).